PIP5K1A (phosphatidylinositol-4-phosphate 5-kinase type 1 alpha)
Diseases named in the same sentence as PIP5K1A in open-access papers (continued):
Sharing a sentence is not in itself a finding about the gene and the disease.
cancer (19 papers, 2014 to 2025). A tumor composed of atypical neoplastic, often pleomorphic cells that invade other tissues. "In the luminal subtype, higher level of PIP5K1α was shown to be associated with high-grade cancers and cancers with poor prognosis, respectively (p = 0.031 and p = 0.004) (n = 606), and such association is similarly observed in the unselected cases." (PMID 30104711, 2019). "PIKFYVE and PIP5K1A are enzymes targeted as therapies for cancer, as their inhibition has been shown to induce autophagy, further suggesting our compounds as inducers of autophagy, as both compounds led to an increase in beclin-1 levels." (PMID 39009412, 2024). "By immunoblot analyses and immunofluorescence imaging, we found that MakA caused reduced expression levels of PIP5K1α and PIP2 in both C. elegans and in different mammalian cancer cells." (PMID 36473840, 2022). "Taken together, our study identifies a novel functional mechanism involving PIP5K1α, confirming that PIP5K1α is an intriguing target for cancer treatment, especially for treatment of CRPC." (PMID 35386201, 2022). "Our study identifies a novel functional mechanism involving PIP5K1α, confirming that PIP5K1α is an intriguing target for cancer treatment, especially for treatment of CRPC." (PMID 35386201, 2022). "In this present study, we used C. elegans, HCT8, DLD1, and CT26 cancer cells as our models to investigate the mechanisms of the effect of MakA on the host PIP5K1α/PI3K/Akt phospholipid signalling." (PMID 36473840, 2022). "Intriguingly, MakA was then found to inhibit the PIP5K1α lipid-signalling pathway in cancer cells, resulting in a decrease in PIP5K1α and pAkt expression." (PMID 36473840, 2022). "In ER+ cancer cells, PIP5K1α acted on pSer-473 AKT, and was in complexes with VEGFR2, serving as co-factor of ER-alpha to regulate activities of target genes including cyclin D1 and CDK1." (PMID 30104711, 2019). "With the caveat that the cell lines tested were derived from different cancers, PIP5K1A mediates growth driven by endogenous oncogenic KRAS in what appears to be an isoform-specific fashion." (PMID 30194290, 2018). "A second TMA that contained biopsies of BPH and cancer tissues from 48 PCa patients was also examined for AR-V7 and PIP5K1α expression." (PMID 27588408, 2016). "AR-V7 expression was predominantly nuclear, whereas PIP5K1α expression was present in both cytoplasm and nucleus of cancer cells." (PMID 27588408, 2016). "Three genes - CHEK1, EPHB3, and PIP5K1A - were increased at least 2 fold in expression in more than 50% of the tumor set compared to non-cancer controls." (PMID 25474241, 2014). "However, the precise role of PIP5K1α in angiogenesis and cancer cell survivals will be systematically investigated in the near future by using in vitro and in vivo models to mimic neoangiogenic process." (PMID 35386201, 2022). "Interestingly, we found a statistically significant correlation between ERα and PIP5K1α expression in primary cancer tissues and metastatic lesions (r2 = 0.513, P < 0.001)." (PMID 33275817, 2021). "We assumed that PIP5K1α may be required for cancer cells to establish growth and survival in the host environment." (PMID 32971916, 2020). "Perhaps related, PIP5K1A was also not identified in whole-genome CRISPR-Cas9 loss-of-function screens of KRAS-mutant cancer cell lines (e.g., ref.59)." (PMID 30194290, 2018). "We demonstrate that targeted deletion of the N-terminal domain of PIP5K1α in CRPC cells results in reduced growth and migratory ability of cancer cells." (PMID 35386201, 2022). "The immunoblot analysis revealed a dose-dependent decrease in PIP5K1α expression in DLD1 and CT26 cancer cells treated with MakA for 48 h, essentially similar to the effect found in HCT8 cells." (PMID 36473840, 2022). "VEGFA, PTEN, PIP5K1A, CDK1, and CCND1 in the panel are key factors involved in the PI3K/AKT pathways important for cancer survival and metastasis." (PMID 33363151, 2020).
cancer (continued). "In this study, we demonstrated that abnormally high expression of the PIP5K1α/AKT pathway led to increased survival and invasiveness of MCF-7 cancer cells." (PMID 30104711, 2019). "We found that MHC-I scores were higher in cancer cells without expression of PIP5K1A, NCKAP1, CYFIP1, DIS3, TBP, and EXCO1." (PMID 39408874, 2024). "PIP5K1α acts upstream of AKT, one of the most frequently altered proteins in human cancers." (PMID 32971916, 2020).
tumor (13 papers, 2014 to 2025). "Furthermore, we demonstrated that the combination of MakA with the PIP5K1α inhibitor ISA-2011B caused a more significant decrease in tumour cell proliferation when compared to HCT8 cells treated with MakA or ISA-2011B alone." (PMID 36473840, 2022). "Further analysis of HCC revealed that PIP5K1A mRNA expression was significantly higher in tumor tissues than that in paired normal tissue." (PMID 40405713, 2025). "PIP5K1A protein levels were significantly higher in tumor tissues than that in normal liver tissues, which was consistent with the mRNA expression." (PMID 40405713, 2025). "It has been reported that exosomal circ_PIP5K1A (phosphatidylinositol-4-phosphate 5-kinase type 1 alpha) was highly expressed in NSCLC tumor samples, serum samples and tumor cells." (PMID 38152652, 2023). "We have previously shown that PIP5K1α is a key regulator that triggers the constitutive activation of PI3K/AKT pathways in PCa cells during tumor growth and invasion." (PMID 34932854, 2022). "Nevertheless, in our previous reported studies, we have shown that overexpression of PIP5K1α promotes tumor growth and invasiveness in mouse xenograft models." (PMID 35386201, 2022). "Consistent with the effects of PIP5K1α knockdown on growth of tumor spheroids, the proportion of the siPIP5K1α cells at G0/G1 was significantly increased as compared with that of sicontrol cells (p < 0.0001)." (PMID 35386201, 2022). "In this study, we investigated the functional aspects of PIP5K1α in tumor progression and in mediating the response of CRPC cells to PIP5K1α-inhibitor treatment." (PMID 35386201, 2022). "We elucidated the role of PIP5K1α and its molecular action in tumor growth and invasion by using C4-2 cells and DU145 cells." (PMID 35386201, 2022). "We found a significant correlation between FcγRIIIa and PIP5K1α in primary tumor and metastatic lesions from PCa patients." (PMID 34932854, 2022). "Overexpression of PIP5K1α promotes tumour growth and invasiveness by increasing the activity of PI3K/Akt in mouse xenograft models." (PMID 36473840, 2022). "We demonstrated that siRNA-mediated knockdown of PIP5K1α significantly reduced tumorigenic ability as determined by tumor spheroid assays in both C4-2 cells and DU145 cells." (PMID 35386201, 2022). "To test the biological consequences of deletion of the N-terminus of PIP5K1α on tumor growth in vivo, we employed the xenograft mouse model." (PMID 35386201, 2022). "Immunohistochemical analysis of tumor tissues further revealed that M3G8‐treated tumors exhibited reduced expression of PIP5K1α and VEGFR2 as compared to that of controls (for PIP5K1α, P = 0.01; for pAKT, P = 0.02; and for VEGFR2, P = 0.01)." (PMID 34932854, 2022). "Overexpression of PIP5K1α promotes tumor growth and invasiveness by increasing the activity of PI3K/AKT in mouse xenograft models." (PMID 35386201, 2022). "The correlation between the expression of ERα and PIP5K1α in tumor tissues was also illustrated using the correlation scatter plot." (PMID 33275817, 2021). "PIP5K1α, pAKT and AR was also highly expressed in primary tumor tissues and metastatic lesions from PCa patients in these cohorts." (PMID 33275817, 2021). "Combined treatment using tamoxifen together with ISA‐2011B led to regression of tumor growth in mice, probably by synergistically blocking elevated ERα and PIP5K1α/AKT pathways." (PMID 33275817, 2021). "We have previously shown that the overexpression of PIP5K1α signaling resulted in aggressive tumor progression in several mouse models." (PMID 32971916, 2020). "We inhibited PIP5K1α by transfecting siRNA for PIP5K1α or control siRNA before subjecting the mono-cultured or co-cultured cells to tumor-spheroid assays." (PMID 32971916, 2020). "The high proportion of CD11b-positive cells was coincident with the high level of expression of VEGF, PIP5K1α and Ser437-pAKT, markers for tumor survival, angiogenesis and metastasis in the center region and in the invasive front of the tumor tissues." (PMID 32971916, 2020).
tumor (continued). "Our present study suggests that tumor-infiltrating cells are likely to be one of the major sources of the increased PIP5K1α and AKT activity observed in PCa." (PMID 32971916, 2020). "In this study, we show that AR-V7 expression positively correlates with PIP5K1α in tumor specimens from PCa patients." (PMID 27588408, 2016). "In the present study, we show that AR-V7 is highly expressed in metastatic tissues from PCa patients and its expression correlates with elevated level of PIP5K1α expression in tumor tissues from PCa patients." (PMID 27588408, 2016). "In addition, using orthotopic liver xenograft tumor models, we demonstrated that PIP5K1A overexpression significantly promoted liver tumor growth." (PMID 40405713, 2025). "In prostate cancer fibroblast and tumor microenvironment models, AR activation has been linked to upregulation of MMP-9/VEGF signaling via PIP5K1α/AKT crosstalk, implicating a molecular axis by which androgen signaling promotes proteolysis and vascular remodeling in tumor stroma." (PMID 41304763, 2025). "Our new finding identifies the N-terminal domain of the lipid kinase PIP5K1α is important to control the growth of PCa, thus may serve as an ideal drug target for designing new PIP5K1α inhibitor to suppress tumor growth by blocking PIP5K1α activity." (PMID 35386201, 2022). "The PIP5K1α-associated PI3K/Akt and the downstream proliferation, survival, and invasion pathways were all targeted by ISA-2011B, which was demonstrated to supress tumour growth and metastasis to distant organs in xenografted mice." (PMID 36473840, 2022). "Our results imply that the intoxication of tumour cells with MakA may result in the inhibition of PIP5K1α activity." (PMID 36473840, 2022). "We found that MakA could inhibit the PIP5K1α/Akt lipid-signalling pathway, resulting in increased expression of the tumour suppressor p27." (PMID 36473840, 2022). "We further showed that the inhibition of PIP5K1α reduced the ability of PCa cells to grow in the presence of myeloid cells, suggesting that tumor cells and the tumor microenvironment may be targeted by using selective kinase inhibitors." (PMID 32971916, 2020). "Therapeutic interventions using a selective inhibitor of lipid kinase PIP5K1α may not only inhibit the growth of primary tumors but may also target the lethal mCRPC within tumor-microenvironment." (PMID 32971916, 2020). "Therapeutic interventions using PIP5K1α inhibitors may not only inhibit tumor invasion and metastasis but also enhance the host immune system." (PMID 32971916, 2020). "However, CRPC tumors lacking the N-terminal domain of PIP5K1α were unable to progress to aggressive tumors and displayed loss of tumor vascularization, in contrast to that of controls in xenograft mice." (PMID 35386201, 2022). "Of course, we noticed that deletion of PIP5K1A, NCKAP1, and CYFIP1 genes also changes gene expression in certain metabolic pathways, such as cholesterol metabolism, which might also contribute to suppression of tumor cell growth induced by deficiency of these molecules." (PMID 39408874, 2024). "Our results showed that PCa cells that were treated with either siRNA for PIP5K1α or its specific inhibitor, ISA-2011B, were unable to survive and produce tumor spheroids, in the presence of U-937 bone marrow cells." (PMID 32971916, 2020). "We showed that PCa cells that were treated with either siRNA for PIP5K1α or its specific inhibitor, ISA-2011B, were unable to survive and produce tumor spheroids, together with bone marrow cells." (PMID 32971916, 2020). "Our study identifies novel cooperative mechanisms involving PIP5K1α, AR-V7, CDK1 and AR, which drive tumor progression and contribute to enzalutamide resistance." (PMID 27588408, 2016). "Taken together, our study identifies novel cooperative mechanisms involving PIP5K1α, AR-V7, CDK1 and AR, which drive tumor progression and contribute to enzalutamide resistance." (PMID 27588408, 2016).
tumor (continued). "Further, the xenograft tumors lacking the N-terminal domain of PIP5K1α exhibited reduced tumor growth and aggressiveness in xenograft mice as compared to that of controls." (PMID 35386201, 2022). "In the absence of functional PTEN, PIP5K1α induces elevated activation of AKT and promotes PC3 tumor growth in xenograft mice." (PMID 27588408, 2016).
infection (2 papers, 2016 to 2021). The state of being infected such as from the introduction of a foreign agent such as serum, vaccine, antigenic substance or organism. "PIP5K1α can influence the internalization and infection of various viruses, such as influenza A virus, foot-and-mouth disease virus, and vesicular stomatitis virus." (PMID 33808870, 2021). "Finally, siRNA-mediated knockdown of Rac1, Arp3, or PIP5K1-α inhibited infection of CHIKV." (PMID 27031835, 2016). "Finally, we confirmed the importance of Rac1:PIP5K1-α complex formation to infection with CHIKV." (PMID 27031835, 2016).
PIP5K1A also shares sentences with these, for which no sentence is quoted: breast tumor (1 paper); diabetes (1); Infertility (1); invasive breast carcinoma (1); leukemia (1); lymphoma (1); obstructive jaundice (1); pheochromocytoma and paraganglioma (1); prostate hyperplasia (1); Prostate Tumor (1); rectum adenocarcinoma (1); stomach cancer (1); testicular germ cell tumor (1); thyroid carcinoma (1).